THBS1 (thrombospondin 1)
Diseases named in the same sentence as THBS1 in open-access papers (continued):
Sharing a sentence is not in itself a finding about the gene and the disease.
bronchopulmonary dysplasia (1 paper, 2025). Bronchopulmonary dysplasia is a chronic respiratory disease that results from complications related to lung injury during the treatment of infant acute respiratory distress syndrome in low-birth-weight premature infants or from abnormal lung development in older infants. "Since bronchopulmonary dysplasia (BPD) involves the inhibition of lung development with altered lung structure and vasculature, differential expression of the THBS-1 gene may impact lung development and pulmonary endothelial cell repair and have an important role in BPD." (PMID 40338233, 2025).
Burkitt lymphoma (1 paper, 2022). A rare form of malignant mature B-cell non-Hodgkin lymphoma. "Analysing gene expression data of Burkitt lymphoma transcriptome sequencing from African patients revealed six biomarkers (ADAMTSL4, SEMA5B, ADAMTS15, THBS2, SPON1 and THBS1) as possible indicators for diagnostic and prognostic targets towards BL management." (PMID 36354023, 2022).
cardioembolic stroke (1 paper, 2022). "Consequently, THBS1 may have relation to cardioembolic stroke." (PMID 36212039, 2022).
Cerebral ischemia (1 paper, 2024). Restriction of arterial blood supply to the brain associated with insufficient oxygenation to support the metabolic requirements of the tissue. "THBS1 is one of the few genes found to be upregulated in both transcriptomic and proteomic data, and we showed that its protein level was upregulated by reperfusion in the brain ECs of mice following cerebral ischemia." (PMID 37789643, 2024). "In addition, the protein level of THBS1 was substantially upregulated upon reperfusion in brain endothelial cells and the peri‐endothelial area in mice receiving cerebral ischemia." (PMID 37789643, 2024).
cerebral microbleeds (1 paper, 2017). Cerebral microbleeds are a group of pathological processes affecting the small arteries, arterioles, capillaries and venules of the brain, as detected by brain imaging techniques. "Interestingly, 30% of Fabry patients show cerebral microbleeds, which together with the downregulated Thrombospondin 1 (Thsd7a) and Thromboxane a2 receptor (Tbxa2r) can be related to a general deficit in blood coagulation pathways." (PMID 29422837, 2017).
choroidal neovascularization (1 paper, 2025). An eye disorder described by the growth of new blood vessels that originate from the choroid through a break in the Bruch membrane into the sub–retinal pigment epithelium (sub-RPE) or subretinal space. "Adult C57BL/6J or Thbs-1–/– mice were treated with daily aspirin (1.25 mg/kg) for 8 weeks before being subjected to laser-induced choroidal neovascularization (CNV)." (PMID 41427444, 2025).
chronic idiopathic urticaria (1 paper, 2020). Chronic form of idiopathic urticaria. "Very recently, THBS1 was demonstrated to promote the inflammatory response of mast cells in chronic idiopathic urticaria and the permeability of human dermal microvascular endothelial cells by regulating the TGF-β/SMAD pathway, the effects of which can be inhibited by miR-194 (Qu, Yang & Liu, 2020)." (PMID 32874785, 2020).
chronic myeloid leukemia (1 paper, 2016). "The significantly enriched pathways included chemokine signaling pathway (which involved CCL2), focal adhesion (which involved THBS1 and THBS2), TGF-beta signaling pathway (which involved THBS1, THBS2, SMAD5, and SMAD6) and chronic myeloid leukemia (which involved TGFBR2 and CCND1)." (PMID 27716259, 2016).
coagulopathy (1 paper, 2019). "As coagulopathy in isolated TBI is associated with increased mortality, D-Dimer, thrombospondin-1, and SCUBE1 could be important prognostic indicators in sTBI." (PMID 31105646, 2019).
congenital glaucoma (1 paper, 2022). "In this study, we report on 3 unrelated and ethnically diverse families with congenital glaucoma, in which the affected members are carriers of missense alleles involving the same THBS1 R1034 residue." (PMID 36453543, 2022). "Identification of THBS1 missense alleles in patients with congenital glaucoma." (PMID 36453543, 2022). "As THBS1 can contribute to the development of vasculature as well as lymphangiogenesis, we first considered abnormalities in angiogenesis, lymphangiogenesis, or SC development, as has been recently shown for congenital glaucoma causing mutations in ANGPT1 and TEK." (PMID 36453543, 2022). "A heterozygous THBS1 missense variant (R1034C), apparently segregating in an autosomal-dominant manner, was initially identified by whole-exome sequencing (WES) in a family of European ancestry with congenital glaucoma (family 1)." (PMID 36453543, 2022).
congestive heart failure (1 paper, 2018). Failure of the heart to pump a sufficient amount of blood to meet the needs of the body tissues, resulting in tissue congestion and edema. "We noted increased SNO modification (–ve RoR value) of three proteins (THBS1, S100A6, abd SH3BGRL2) in ChD patients in this study, as well in congestive heart failure (CHF) patients of idiopathic etiology in a previous study." (PMID 30697201, 2018).
corticotropinomas (1 paper, 2025). "New research suggests that secreted angioinhibitory factor thrombospondin-1 (TSP-1) expression is significantly lower in patients with corticotropinomas versus healthy individuals, and is a direct target of miR-449c." (PMID 40362297, 2025).
Cushing syndrome (1 paper, 2023). Cushing's syndrome (CS) encompasses a group of hormonal disorders caused by prolonged and high exposure levels to glucocorticoids that can be of either endogenous (adrenal cortex production) or exogenous (iatrogenic) origin. "THBS1 is a glucocorticoid responsive protein in humans and was elevated in human patients being treated with prednisolone and with Cushing's syndrome." (PMID 37279179, 2023).
cyst (1 paper, 2022). A sac-like closed membranous structure that may be empty or contain fluid or amorphous material. "Moreover, THBS1 was sufficient to induce the morphological change, since its ectopic expression in WT organoids also led to cyst development, to the same extent as T-cM." (PMID 35543624, 2022).
disc degeneration (1 paper, 2025). "Bone morphogenesis-related genes (TGFB2, BMP4, and THBS1) were enriched in NPPCs, suggesting that NPPCs undergo osteogenic differentiation during the progression of disc degeneration in C2." (PMID 40883814, 2025).
dissection (1 paper, 2021). The separation and isolation of tissues for surgical purposes, or for the analysis or study of their structures. "Thrombospondin 1 activates macrophage differentiation and SMC apoptosis in human aortic dissection while decreases miR-25-5p expression in vascular SMCs." (PMID 33460396, 2021).
dysferlinopathy (1 paper, 2020). "Studies in the muscle of both human and mouse models of dysferlinopathy suggest dysferlin deficient muscle plays a role in this inflammation by releasing thrombospondin-1." (PMID 33246442, 2020).
endometrioid ovarian cancer (1 paper, 2021). "Two genes, LOX and THBS1, did show correlation with a positive clinical outcome in endometrioid ovarian cancer despite a lack of significance between the high and low expression levels." (PMID 34868914, 2021).
enteropathies (1 paper, 2023). "The data reported here show potential for THBS1 to be used as a diagnostic test in enteropathies in cats, where the diagnosis typically relies on invasive surgical or endoscopic intestinal biopsies." (PMID 37279179, 2023).
ependymoma (1 paper, 2009). A WHO grade II, slow growing tumor of children and young adults, usually located intraventricularly. "The tumors suppressor genes RASSF1, CDKN2A, CDKN2B, p14ARF and TP73, as well as other genes potentially involved in the tumorigenesis of ependymomas, such as CASP1, MGMT, TIMP3 and THBS1 are epigenetically silenced by aberrant promoter methylation in subsets of ependymomas." (PMID 19333441, 2009).
Fabry disease (1 paper, 2021). Fabry disease (FD) is a progressive, inherited, multisystemic lysosomal storage disease characterized by specific neurological, cutaneous, renal, cardiovascular, cochleo-vestibular and cerebrovascular manifestations. "As THBS1 regulates vessel stabilization, its overexpression has been shown to suppress vascular growth and expand vessel diameter, suggesting that it could be associated with dysfunctional angiogenesis, like in Fabry disease." (PMID 34680548, 2021).
Fibroadenoma (1 paper, 2025). A benign tumor of the breast characterized by the presence of stromal and epithelial elements. "At 25 weeks, corresponding to fibroadenoma emergence, the Diet group showed increased expression of MMP2 (p = 0.036), THBS1 (p = 0.03), TWIST1 (p = 0.015), and PAI-1 (p < 0.001)." (PMID 40806434, 2025).
fungal infections (1 paper, 2024). "Additionally, other studies have found that hyperferritinemia and elevated plasma levels of adhesion molecules such as soluble intercellular adhesion molecule-1 (sICAM-1), thrombospondin-1, and vinculin promote invasive fungal infections." (PMID 39176311, 2024).
fungal meningitis (1 paper, 2022). Meningitis caused by fungal agents which may occur as opportunistic infections or arise in immunocompetent hosts. "C. neoformans treatment increased the expression of inflammation-related proteins, including pentraxin 3 (PTX-3), thrombospondin-1 (TSP-1), and IL-8, compared to C. glabrata infection, which does not commonly cause fungal meningitis." (PMID 35806421, 2022).
hearing loss (1 paper, 2025). "Of note, the thrombospondin (THBS1) gene, which plays important, well-established roles in hearing loss, has extensive proximal HCMV-induced TEAD1-binding loss and HCMV-induced gene and protein level reduction." (PMID 40928347, 2025).
HIV-1 infection (1 paper, 2019). The type species of lentivirus and the etiologic agent of acquired immunodeficiency syndrome (AIDS). "Additionally, ACTB and ACTG1 are known to inhibit viral assembly and production, and THBS1 is known to inhibit HIV-1 infection." (PMID 30626383, 2019).
hypertensive heart disease (1 paper, 2016). Abnormal enlargement of the heart resulting from long-standing hypertension. "The expression of THBS1 (and -2 and -4 isoforms) was increased in hypertensive heart disease." (PMID 27635260, 2016).
Hypoglycemia (1 paper, 2021). A decreased concentration of glucose in the blood. "At hypoglycemia, however, four proteins changed in controls from baseline [Thrombospondin-1 (p < 0.014), platelet factor-4 (p < 0.01), Platelet basic protein (p < 0.008), and Vitamin K-dependent protein-C (p < 0.00003)], and one protein changed in T2D [Vitamin K-dependent protein-C, (p < 0.0002)]." (PMID 34248840, 2021).
inflammatory bowel disease (1 paper, 2023). A spectrum of small and large bowel inflammatory diseases of unknown etiology. "Among these genes, Dusp4, Epha2, Atp11a, and Tns4 are reported to be overexpressed in human CRC, while the expression of Thbs1 is increased in patients with inflammatory bowel disease." (PMID 37296911, 2023).
injury (1 paper, 2021). Damage inflicted on the body as the direct or indirect result of an external force, with or without disruption of structural continuity. "THBS1-knockout mice displayed higher BBB disruption, neuronal death, and hippocampal-dependent learning impairments after traumatic brain injury." (PMID 33874954, 2021).
Insulinoma (1 paper, 2019). "Indeed, in rat INS-1 (Insulinoma cell line 1) cells, the expression of miR-182-5p decreased after palmitate treatment and modulated the expression of Thrombospondin 1 (THBS‐1), a multifunctional glycoprotein associated to insulin resistance and β cell function." (PMID 31861156, 2019).
intracerebral hemorrhage (1 paper, 2019). A cerebrovascular disorder characterized by bleeding into one or both cerebral hemispheres including the basal ganglia and the cerebral cortex. "Thrombospondin-1 is a thrombin-sensitive, anti-angiogenic factor whose expression is increased after intracerebral hemorrhage." (PMID 31105646, 2019).
kidney cancer (1 paper, 2014). Primary or metastatic malignant neoplasm involving the kidney. "We used quantitative RT‐PCR to measure the levels of three TGF‐beta pathway components (TGFB2, INHBA, and SMAD3) and two TGF‐beta targets (THBS1 and CDKN2B) which were previously found to be significantly lower in FLCN‐deficient kidney cancer cells and tumors." (PMID 25121506, 2014).
Klebsiella pneumonia (1 paper, 2022). An pneumonia caused by infection with Klebsiella. "For example, THBS1 loss promoted the clearance of lung Klebsiella pneumonia, decreased lung inflammation burden, and enhanced the innate immune responses against Klebsiella pneumonia infection." (PMID 36387401, 2022).
left ventricular hypertrophy (1 paper, 2024). Enlargement of the LEFT VENTRICLE of the heart. "This study revealed that in the context of CKD, both indoxyl sulphate and the extracellular matrix protein thrombospondin-1 (TSP1) promote features of left ventricular hypertrophy (LVH) through the activation of the aryl hydrocarbon receptor (AhR)." (PMID 38473905, 2024).
leiomyosarcoma (1 paper, 2014). An uncommon, aggressive malignant smooth muscle neoplasm, usually occurring in post-menopausal women. "In leiomyosarcoma-derived cell lines it could be demonstrated that hepatocyte growth factor (HGF) induces a decrease in anti-angiogeneic THBS1 and an increase in VEGFA." (PMID 24398114, 2014).
liver dysfunction (1 paper, 2016). "Indeed, platelet-derived α-granules contained both Thrombospondin-1 and VEGF, and human data demonstrated that high Thrombospondin-1 and low VEGF were predictors of liver dysfunction after resection." (PMID 27409608, 2016).
low grade glioma (1 paper, 2025). A grade I or grade II glioma arising from the central nervous system. "Other relevant pathways in cancer, such as focal adhesion, cytoskeleton regulation, and chemokine signalling (VCL, THBS1-4, FLNA, LAMA2/4/5, HSPG2), might also be influenced indirectly by changes in the WWOX/HIF1A ratio, potentially impacting the overall prognosis of low-grade glioma patients." (PMID 41007296, 2025).
lung adenoma (1 paper, 2024). A benign, well circumscribed epithelial neoplasm that arises from the bronchus or the lung parenchyma. "Similarly, in an in vivo model of lung adenoma, THBS1 expression decreased proliferation and promoted apoptosis." (PMID 38339060, 2024).
mammary adenocarcinomas (1 paper, 2021).
mesothelioma (1 paper, 2021). A usually malignant and aggressive neoplasm of the mesothelium which is often associated with exposure to asbestos. "In mesothelioma cells, among the angiogenesis-related proteins, angiopoietin-1, thrombospondin-1 (TSP-1), and tissue inhibitor of metalloproteinases-1 (TIMP-1) were significantly downregulated upon SDC-1 over-expression, whereas IL-8 was upregulated upon SDC-1 silencing." (PMID 33562126, 2021).
metastatic carcinoma (1 paper, 2022). A carcinoma which has spread from the original site of growth to another anatomic site. "Tumor cell line validation also showed higher expression of THBS1 and SERPINE1 in metastatic cancer cell lines." (PMID 35372476, 2022).
multiple sclerosis (1 paper, 2023). A progressive autoimmune disorder affecting the central nervous system resulting in demyelination. "Thrombospondin-1 may counter inflammatory processes in multiple sclerosis, participate in the proliferation and differentiation of neural progenitor cells, mediate axon regeneration and contribute to formation and modulation of dendritic spines." (PMID 37055866, 2023).
Myotonia (1 paper, 2025). An involuntary and painless delay in the relaxation of skeletal muscle following contraction or electrical stimulation. "Treatment of HSALR mice with TG corrected a group of abnormally expressed genes in HSALR muscle, including chloride channel 1, which is associated with myotonia, and a circulating glycoprotein, thrombospondin 1 (THBS1)." (PMID 41226794, 2025).
nephritis (1 paper, 2023). Inflammation of renal tissue. "Inhibition with THBS1 antisense oligonucleotides or peptides blocking THBS1-TGF-β1 interactions markedly suppressed renal ECM expansion and nephritis in rats." (PMID 37371758, 2023).
nephrolithiasis (1 paper, 2018). The presence of a calculus in the pelvis of the kidney; this is most often composed of mineral salts and proteins. "In this study, the induction of THBS1 in the oxalate group indicated its potential role in nephrolithiasis." (PMID 29950996, 2018).
oligodendroglioma (1 paper, 2009). A well-differentiated (WHO grade II), diffusely infiltrating neuroglial tumor, typically located in the cerebral hemispheres. "Other genes hypermethylated in oligodendrogliomas include the tumor suppressors CDKN2A, CDKN2B and RB1, as well as DAPK1 (death-associated protein kinase 1), ESR1 (estrogen receptor 1), THBS (thrombospondin 1) and TIMP3 (tissue inhibitor of metalloproteinase 3)." (PMID 19333441, 2009).
optic neuritis (1 paper, 2019). Optic neuritis is inflammation of the optic nerve, the nerve that carries the visual signal from the eye to the brain.The conditionmay cause sudden, reduced vision in the affected eye(s). "Together, these data revealed that during optic neuritis, astrocytes in ON undergo important molecular changes, characterized by upregulation of THBS1 in early EAE, and upregulation of C3, in late EAE." (PMID 31292459, 2019).
ovarian endometriosis (1 paper, 2009). A non-neoplastic disorder characterized by the growth of endometrial tissue in the ovaries. "Thrombospondin-1 serum levels is correlate with pelvic pain in patients with ovarian endometriosis." (PMID 19917115, 2009). "Pain symptoms in ovarian endometriosis is not correlated with thrombospondin-1 serum levels." (PMID 19917115, 2009).
ovarian tumors (1 paper, 2021). "Among possibilities, thrombospondin-1 (TSP-1) is a matricellular protein being overexpressed within ovarian tumors, for which interaction with CD47 receptor was reported as directly inhibiting adaptive immunity." (PMID 34638503, 2021).
overnutrition (1 paper, 2024). An imbalanced nutritional status resulting from excessive intake of nutrients. "In the setting of long-term overnutrition, THBS1 promotes stromal expansion characterized by increased THY1+ FAPs, aberrant ECM deposition, and elevated intramuscular adiposity." (PMID 38954467, 2024).
pancreatic ductal adenocarcinoma (1 paper, 2018). An infiltrating adenocarcinoma that arises from the epithelial cells of the pancreas. "The proteomic stromal signature of pancreatic ductal adenocarcinoma (PDA) shows a contribution of the annexin A6/LDL receptor-related protein 1/thrombospondin 1 (ANXA6/LRP1/TSP1) complex in tumour cell crosstalk." (PMID 29462943, 2018).
pediatric tumors (1 paper, 2013). "In contrast, our findings showed that hypermethylation of a single locus of THBS1 is sufficient for the differentiation of CCSK from other pediatric tumors and it could serve as a robust diagnostic marker for this tumor." (PMID 23638012, 2013).